INS (insulin)
Diseases named in the same sentence as INS in open-access papers (continued):
Sharing a sentence is not in itself a finding about the gene and the disease.
Glucose intolerance (continued). "Hence, mice heterozygous for a kinase-dead knock-in mutation in the gene encoding p110α (p110α KI) displayed insulin resistance and moderate glucose intolerance at young age." (PMID 28795262, 2017). "Consistent with results of this study, earlier diagnosis of GDM in pregnancy before increasing resistance to insulin between 16 and 26 weeks of gestation is reported as a common risk factor associated with progression to later glucose intolerance in women with GDM." (PMID 28491872, 2017). "Glucose intolerance could also have been caused by impaired insulin-independent and/or insulin-dependent glucose uptake by metabolic tissues." (PMID 28374068, 2017). "We tested the hypothesis that CM increases the risk for prediabetic state due to glucose intolerance, reduced insulin sensitivity, and beta cell function." (PMID 28713332, 2017). "However, as the gestation progresses the effect of placenta peptides; Progestrone, estradiol, leptin and glycated haemoglobinon insulin predisposes the women to glucose intolerance and eventually to overt GDM." (PMID 28732072, 2017). "Thus, how efficiently glucose promotes its own disposal unrelated to insulin action predicts the future risk of developing glucose intolerance." (PMID 28469281, 2017). "Interestingly, lack of thyroid hormone is also associated with a decrease in peripheral insulin sensitivity and glucose intolerance and treatment of hypothyroidism has been shown to improve insulin sensitivity." (PMID 27686165, 2016). "GC actions are cell- and tissue-specific and vary depending on many aspects including dosage, duration of treatment (short- or long-term), previous individual susceptibility (e.g., glucose intolerance or reduced insulin sensitivity), and the species evaluated (e.g., human, rodents)." (PMID 27527232, 2016). "While there have been conflicting reports on how a HF diet impacts bone in C57BL/6 mice, the results of this study indicate the skeletal response may be linked to the duration of disrupted insulin signaling and glucose intolerance." (PMID 26146567, 2015). "While we did not measure changes in insulin signaling in this cohort of animals, others have shown consistently that rapamycin affects the insulin pathway in much the same manner in multiple strains of mice including C57BL6, namely creating glucose intolerance, but causing insulin sensitivity." (PMID 25414638, 2014). "It has been suspected from animal studies that loss of Cx36 is phenotypically similar to a prediabetic condition characterized by glucose intolerance, diminished insulin oscillations and first and second phases of insulin secretion, and a loss of beta-cell mass." (PMID 23936417, 2013). "Glucose intolerance could reflect reduced insulin sensitivity of peripheral tissues in SERT-deficient mice." (PMID 22412882, 2012). "Along with the decreased insulin release from pancreas, loss of significant amount of fat mass might have also contributed to the glucose- intolerance in lean rats (adipose tissue being one of the main organs for insulin- stimulated glucose uptake)." (PMID 23284633, 2012). "The Rd that is mainly determined by muscles in the hyperinsulinemic-euglycemic clamp was significantly lower in the knockin mice than their wild-type littermates, suggesting that the glucose intolerance in the knockin mice was mainly caused by reduced insulin-mediated glucose transport in muscle." (PMID 21195350, 2011). "Indeed, in ML mice glucose intolerance was associated with an increased plasma insulin concentration 15 min after the glucose challenge." (PMID 21698161, 2011). "Interestingly, PANDER-deficient mice show glucose intolerance due to impaired insulin secretion from pancreatic β cells." (PMID 21113299, 2010).
Glucose intolerance (continued). "However, in a genetic model of Zn deficiency where animals harbor a mutation in the Zn transporter, Znt8, glucose intolerance due to elevated insulin degradation was observed, suggesting that genetic changes leading to dysregulated Zn metabolism do not mimic a dietary deficiency of the metal." (PMID 40901282, 2025). "Additionally, Atp10A deficiency in mice may result in glucose intolerance, reduced insulin sensitivity, and hyperinsulinemia." (PMID 38382846, 2024). "Furthermore, age and female sex are associated with glucose intolerance in CF and reduced insulin sensitivity, hence we cannot reject that there may have been some confounding by these factors." (PMID 39093413, 2024). "Although we have not investigated offspring pancreatic tissues, we hypothesize that alterations in the development of the pancreas may underlie the susceptibility of males for glucose intolerance and modest insulin sensitivity in eTRF offspring after HFHS feeding." (PMID 37808966, 2023). "Moreover, reports by Gad and El-Maddawy, as well as Kamal, explained that glucose intolerance might be caused by either a defect in secretion of insulin (T1DM disorder) or a defect in insulin sensitivity (T2DM disorder)." (PMID 37375806, 2023). "In addition, the elevation of ghrelin might be one of the possible causes of suppressing insulin elevation and glucose intolerance in male RUPP rats." (PMID 36109770, 2022). "Taken together, these results reinforce the ideas that overtraining may be associated with glucose intolerance, the liver may act as a compensatory organ for glucose homeostasis and improve major proteins involved in hepatic insulin signaling, which induces hepatic glycogen accumulation." (PMID 34200732, 2021). "Recent studies showed that MG injection of Sprague–Dawley rats may cause glucose intolerance, reduce the insulin-stimulated glucose uptake in adipose tissue, and result in pancreatic dysfunction and that oral administration of MG at 300 mg/kg/day may induce inflammation in the pancreatic β-cells." (PMID 34371651, 2021). "Regarding the effects on insulin sensitivity, recent studies of our group in a Ptn knock-out mice model revealed that deletion of Ptn accelerates the development of age related whole-body glucose intolerance, favoring a prediabetic state and predisposing these animals to develop T2DM." (PMID 34071721, 2021). "The mother's oGTT showed mild glucose intolerance; the mother also had gestational diabetes during the pregnancy, consistent with previous reports of gestational diabetes and impaired glucose‐stimulated insulin secretion in patients with KATP channel inactivating mutations." (PMID 31464105, 2019). "Indeed, HFD‐fed ASK1Δhep mice showed slightly impaired glucose tolerance as well as increased plasma insulin levels when compared to ASK1F/F mice indicating that ASK1 deficiency may enhance HFD‐induced glucose intolerance." (PMID 31595673, 2019). "Therefore, we speculated that the progressive glucose intolerance of PEE offspring from PW12 to 24 might be due to the loss of sensitivity to endogenous insulin and IGF1." (PMID 30778335, 2019). "Therefore, we conducted a retrospective study to evaluate if androgen excess as indicated by high FAI characterizes a higher prevalence of glucose intolerance, and the potential associations between androgen excess, insulin sensitivity, and islet β-cell function." (PMID 29707577, 2018). "Our data therefore highlight that variations in underlying maternal insulin secretion and sensitivity together with the degree of metabolic stress posed by factors specific to the pregnancy, all contribute to variations in postpartum risk for glucose intolerance." (PMID 25180037, 2014). "Therefore, in the long run, a prolonged small decrease in [Ca2+]ER in combination with other ER stress susceptibility factors, such as excessive insulin biosynthesis, may ultimately result in beta-cell failure, apoptosis, and severe glucose intolerance." (PMID 25053525, 2014).
Glucose intolerance (continued). "The findings ofOh and Barrett-Connor suggest that VDR genevariant may be associated with glucose intolerance independentof defective insulin secretion and with IR.Mahmoudi indicated that VDR gene variant mayaffect PCOS development as well as IR in womenwith PCOS." (PMID 24520473, 2013). "It is possible that whole-body glucose intolerance induced by KD feeding might be caused by the change of glucose metabolism in other tissues including liver and muscle, in addition to the impairment of insulin signaling in white adipose tissue." (PMID 23874946, 2013). "Pioneer studies in mice have shown that aging promotes glucose intolerance, despite an increase in glucose-induced insulin secretion." (PMID 41543803, 2026). "The predictor variables can be considered in three groups: those with insulin and glucose intolerance (Mbd2, Tnip1, Itgb4, and Iffo2), those with BMR (1010001N08RiK and Clvs2), and those associated with Tb (Calb2)." (PMID 41432313, 2026). "These mice displayed glucose intolerance and defective insulin secretion, particularly after oral glucose challenge, indicating impaired incretin responses." (PMID 41480766, 2026). "DNA methylation at several CpG sites was sensitive to glucose intolerance and circulating insulin levels, consistent with the impact of this nutrient sensing pathway on ageing." (PMID 41432313, 2026). "Further testing of incretin responses in vivo using meal tolerance test (MTT) confirmed glucose intolerance and blunted insulin secretion 6 weeks after Tmx." (PMID 41480766, 2026). "Inducible deletion of JNK3 in mature β cells results in glucose intolerance and defective insulin secretion after oral glucose and nutrients." (PMID 41480766, 2026). "Deletion of JNK3 in β cells results in glucose intolerance and defective insulin secretion in response to oral glucose and incretin stimulation." (PMID 41480766, 2026). "Our findings revealed that oxidative stress-induced REDD2 acts as a negative regulator of β-cell mass and regulation, contributing to glucose intolerance by decreasing secreted insulin." (PMID 40409543, 2025). "During the test, the higher insulin levels in Inhbe-KO mice suggested that the glucose intolerance of Inhbe-KO mice resulted from decreased insulin sensitivity." (PMID 39948368, 2025). "Subsequent generational analysis revealed that HFD induced glucose intolerance and reduced insulin sensitivity in all generations." (PMID 41220714, 2025). "The oral glucose tolerance test (OGTT), while used primarily to diagnose glucose intolerance, by measuring blood glucose and insulin levels at intervals after a glucose oral load, can offer insights into glucose tolerance and insulin dynamics." (PMID 41463398, 2025). "These drugs interfere with insulin signaling pathways, induce oxidative stress, or modulate glucose and lipid metabolism, leading to impaired insulin sensitivity and glucose intolerance." (PMID 41567335, 2025). "These animals displayed profound glucose intolerance, impaired insulin secretion and sensitivity, and elevated hepatic gluconeogenesis, evidenced by increased expression of PEPCK and G6Pase alongside reduced glucokinase (GCK) activity." (PMID 41438219, 2025). "These transcriptional alterations provide a mechanistic explanation for the severe glucose intolerance, defective insulin secretion and proinsulin processing defects observed in Chd3/4Δβ mice." (PMID 41282155, 2025). "For the final diagnosis of T2D, insulin release by pancreatic β-cells must be insufficient to fully compensate for decreased insulin sensitivity, leading to glucose intolerance." (PMID 39981084, 2025). "In young mice with a partial defect in liver insulin signaling induced by p110α deletion, we observed consistent glucose intolerance and an enhanced neoglucogenic rate." (PMID 40228209, 2025).
Glucose intolerance (continued). "They exhibit consistent glucose intolerance levels and a compromised insulin response to glucose, (Östenson & Efendic 2007), reflecting the inability of beta cells to cope with increased insulin demands." (PMID 41244237, 2025). "Here, we report that the loss of skeletal muscle IPMK (henceforth referred to as MKO) disrupts insulin sensitivity and lipid utilization, leading to increased body weight, glucose intolerance, and reduced exercise tolerance." (PMID 40141045, 2025). "The participants on oral medication or insulin had higher odds of developing postpartum glucose intolerance." (PMID 41523956, 2025). "Consistent with what we reported before, morin significantly improved glucose intolerance and insulin sensitivity in fructose-fed rats, as assessed by the oral glucose tolerance test (OGTT) and insulin tolerance test (ITT)." (PMID 41471373, 2025). "We also found that Ptgr3 knockout mice displayed markedly improve insulin sensitivity and glucose intolerance (unpublished data)." (PMID 40119175, 2025). "Meantime, inflammation can disrupt the insulin signaling pathway and mediate glucose intolerance, with TNF-α further exacerbating metabolic disorders by interfering with the PI3K-Akt signaling pathway." (PMID 40871693, 2025). "Although leptin enhances peripheral insulin sensitivity and β-cell function and suppresses food intake via signaling satiety in the non-pregnant state, pregnancy is associated with progressive leptin insensitivity which may promote insulin insensitivity and glucose intolerance." (PMID 40235646, 2025). "Black tea extract significantly lowered blood glucose level and ameliorated glucose intolerance.Increased serum insulin levels." (PMID 40647906, 2025). "TRAPα is highly expressed in human and mouse pancreatic cells; TRAPα-KO decreases circulating INS, resulting in age-related glucose intolerance." (PMID 40392602, 2025). "It has also been reported that mice that are continually subjected to lard-based HFD exploit glucose intolerance and decreased insulin sensitivity." (PMID 40906133, 2025). "Here, for the first time, we show that breastfeeding dam’s consumption of MG, AGEs precursor, leads the offspring to the onset of early life glucose intolerance and impaired basal and stimulated insulin secretion." (PMID 40001928, 2025). "These animals had glucose intolerance, elimination of amino acid–stimulated insulin secretion, and severe reduction of GSIS." (PMID 40971442, 2025). "Resistin is an adipocytokine-derived endocrine hormone that was originally named for its role in impairing the molecular effect of insulin and inhibiting hepatic gluconeogenesis, resulting in glucose intolerance in rodents." (PMID 40699617, 2025). "Glucose intolerance, reduced insulin secretion, and downregulation of β-cell transcripts are hallmarks of declining β-cell health and function." (PMID 40073934, 2025). "In the subsequent pregnancy, physiological insulin demand increases; women with depleted β-cell reserve cannot compensate, leading to glucose intolerance and s-GDM." (PMID 41427042, 2025). "Although type II is mediated by the prevalence of glucose intolerance and the peripheral cells' decreased sensitivity to insulin." (PMID 40585503, 2025). "Moving beyond its canonical function in xenobiotic metabolism, recent findings reveal that AHR activation impairs hepatic insulin signaling, thereby contributing to systemic insulin resistance and glucose intolerance." (PMID 41516226, 2025). "Our results suggest that an age-related decline in insulin secretion plays an important role in the development of glucose intolerance in older Japanese adults." (PMID 40002793, 2025). "Pancreatic β cell–specific deletion of BAF60a (i.e., β cell–specific BAF60a KO [BaβKO]) leads to chromatin and transcriptional changes resembling those observed in diabetic islets, accompanied by impaired biphasic insulin secretion and glucose intolerance." (PMID 41052246, 2025).
Glucose intolerance (continued). "This imbalance can result in altered insulin sensitivity and peripheral inflammation, potentially explaining the consistent associations among reduced HRV, glucose intolerance, and inflammation." (PMID 40964166, 2025). "The glucose intolerance and reduced glucose stimulated insulin secretion in the OC-/- mice, which was supported by smaller pancreatic islets, reduced insulin expression in β cells and a decrease in β cell proliferation in the absence of osteocalcin." (PMID 41516047, 2025). "Animal experiments have shown that overexpression of human IGFBP-3 or its mutant devoid of IGF-binding ability leads to glucose intolerance with different effects on insulin secretion, insulin sensitivity, and lipid homeostasis in aging mice." (PMID 40027189, 2025). "Collectively, these animal studies suggest a possible role of AhR/CYP1 activation in glucose intolerance, impaired insulin secretion, pancreatic islet dysfunction, and, consequently, the development of DM." (PMID 40408591, 2025). "For instance, rats subjected to HFD for extended periods not only exhibited glucose intolerance but also impairments in insulin homeostasis." (PMID 41292131, 2025). "Chemerin is activated by serine proteases and inflammation, exacerbating glucose intolerance and disturbing insulin signaling." (PMID 39812542, 2025). "Mice models of GDM have further shown that even transient glucose intolerance during pregnancy can programme increased adiposity and altered insulin sensitivity in offspring’s adipose tissue." (PMID 40603555, 2025). "TGFβ, through Smad3 (small mothers against decapentaplegic 3), induces increased body weight, glucose intolerance, hepatic lipid accumulation, and reduced insulin sensitivity in mice fed a high-fat diet." (PMID 40985048, 2025). "We recently found that mice with selective deletion of Trpm7 in β‐cells develop glucose intolerance and declines in insulin secretion, primarily due to the impaired enzymatic activity of this protein." (PMID 40275767, 2025). "A previous study reported that PCOS women with glucose intolerance exhibited higher BMI, waist circumference, blood pressure, triglyceride levels, free testosterone levels, fasting glucose levels, HbA1c and insulin levels." (PMID 40094911, 2025). "The present study showed that the administration of KN-93 and acremomannolipin A significantly decreased blood levels of glucose and insulin and ameliorated glucose intolerance in HFD-fed mice." (PMID 40662171, 2025). "Although the pathophysiological relationship between muscle loss and prognosis is not fully understood, several studies have suggested associations with a high catabolic state, impaired cytokines, and insulin signaling, leading to glucose intolerance." (PMID 40712242, 2025). "Liver-specific loss of adropin gene in mice leads to metabolic disturbances characterized by glucose intolerance, systemic insulin resistance, enhanced adiposity, and transcriptional activation of lipogenic pathways in the liver." (PMID 41465308, 2025). "At the onset of pregnancy, these mice exhibit normal glucose levels, but as pregnancy progresses, dams develop glucose intolerance as a consequence of the impaired insulin secretion while insulin demands are increasing." (PMID 40021748, 2025). "OS prompts mitochondrial and endoplasmic reticulum stress, leading to organelle dysfunction and protein uncoupling, which contribute to glucose intolerance, impaired insulin signalling, and apoptotic cell injury." (PMID 40887321, 2025). "This increase in insulin production protects against the glucose intolerance encountered during pregnancy." (PMID 40362828, 2025). "At animal level, deletion of MCT1 in macrophages exacerbates glucose intolerance, suppresses insulin secretion and increases islet cell death in high-fat diet fed mice." (PMID 40660708, 2025).